SOSTDC1 (sclerostin domain containing 1)
Diseases named in the same sentence as SOSTDC1 in open-access papers (continued):
Sharing a sentence is not in itself a finding about the gene and the disease.
tumor (27 papers, 2010 to 2025). "The deficiency of SOSTDC1 correlated with greater tumour size and treatment with recombinant SOSTDC1 effectively blocked WNT signalling components which contribute to cell proliferation, indicating its antagonistic role against Wnt pathway." (PMID 34997107, 2022). "Overall, Sostdc1 downregulation was associated with poor prognosis and tumour aggressiveness in several types of cancer." (PMID 36338475, 2022). "The tumor suppressive function of SOSTDC1 is associated with upregulation of p21Cip and p27Kip, which may interfere with Rb-E2F signaling and disrupt the transactivating activity of E2F." (PMID 27087917, 2016). "ITGA2hi‐PTC cells were increased in PPTC samples and exhibited high expression of ITGA2, KRT6A, SOSTDC1, KRT6B, and KRT14, genes associated with tumor progression." (PMID 40985182, 2025). "We found that SOSTDC1‐knockdown and treatment with Olaparib significantly decreased tumor volume, the BTIC population, and absolute BTIC numbers." (PMID 38864559, 2024). "SOSTDC1 is a secreted protein downregulated in many primary tumors and usually inhibits the tumor progression." (PMID 38864559, 2024). "SOSTDC1 expression is positively related to tumor malignancy and a poor patient prognosis in TNBC patients." (PMID 38864559, 2024). "Among these genes, SPINT2, LNX1, FOXA2, and SOSTDC1 were reported to be related to tumor progression, whereas TYROBP, TREM2, IL23R, CSF2RB, TRAF1, and TGFBR1 were closely associated with immune response." (PMID 36611170, 2023). "In NSCLC bone metastatic lesions, Sostdc1 was downregulated compared to primary tumours, and low Sostdc1 expression predicted a poor NSCLC prognosis." (PMID 36338475, 2022). "Sostdc1 plays an inhibitory role in tumourigenesis, and its downregulation enhances cancer cell proliferation, colony formation, and tumour expansion." (PMID 36338475, 2022). "SOSTDC1, through its down-regulation, provokes poor prognosis, tumor invasion, and low survival rate in multiple cancer types." (PMID 35333898, 2022). "Sostdc1 is a BMP/Wnt antagonist that often functions as a tumor suppressor, but was reported to promote invasion and liver metastasis in the case of colorectal cancer." (PMID 34785704, 2021). "Mechanistically, SOSTDC1 inhibits tumor progression by blocking the Wnt-β-catenin axis and facilitating T cell differentiation This finding suggests that SOSTDC1 is a potential prognostic biomarker for NSCLC bone metastasis." (PMID 34722241, 2021). "Immunohistochemistry was used to compare the presence of Sostdc1 protein expression in naïve (non-tumour) murine tibiae sections to those infiltrated with 5TGM1 cells." (PMID 30776499, 2019). "In prostate cells, researchers have found that SOSTDC1 regulates the levels of hepcidin by inhibiting BMP and Wnt signaling, and the promoter methylation of SOSTDC1 is associated with tumor recurrence in PCa." (PMID 28938548, 2017). "Sclerostin domain containing protein 1 (SOSTDC1) has been found to be tumor-suppressive in several types of cancers." (PMID 27087917, 2016). "Of note, accumulating studies have revealed that SOSTDC1 acts as a tumor suppressor in several types of cancers." (PMID 27087917, 2016). "Over-expression of SOSTDC1 in NSCLC cells significantly inhibited tumor growth in vivo, further supporting the role of SOSTDC1 in NSCLC as a tumor suppressor gene." (PMID 27087917, 2016). "In wilms tumor, SOSTDC1 is lost as a result of a 7p21 homozygous deletion, which led to accelerate angiogenesis and activation of Wnt signaling." (PMID 27087917, 2016). "To investigate the biological effect of ectopic over-expression of SOSTDC1 on tumor growth in vivo, we proceeded with the research through the establishment of a subcutaneous xenograft tumor model in nude mice." (PMID 26378658, 2015). "The growth curve revealed a dramatic decrease of tumor size in the group with SOSTDC1 over-expression." (PMID 26378658, 2015).
tumor (continued). "An increasing number of studies have demonstrated that SOSTDC1 is dysregulated and acts as a tumor suppressor in some kinds of human cancers." (PMID 26378658, 2015). "There was significant correlation between SOSTDC1 expression and tumor-node-metastasis staging (p =0.008)." (PMID 26378658, 2015). "The tumor size and weight of the SOSTDC1 over-expression group was smaller than that of control group." (PMID 26378658, 2015). "Sclerostin domain containing protein 1 (SOSTDC1) is down-regulated and acts as a tumor suppressor in some kinds of cancers." (PMID 26378658, 2015). "Direct sequencing also confirmed that LOH directly affects SOSTDC1 in patients W-733 and W-8188, as every heterozygous SNP in the normal was lost in the tumor." (PMID 21080955, 2010). "We mainly explored the expression patterns and functional mechanisms of SOSTDC1 on tumor cells." (PMID 38864559, 2024). "Moreover, in vivo xenograft experiments showed that SOSTDC1 knockdown significantly inhibited tumor growth, meanwhile SOSTDC1 overexpression promoted tumor outgrowth." (PMID 38864559, 2024). "On the other hand, more systemic studies would be needed to explore whether other molecules or pathways are also involved in mediating the tumor-suppressive function of SOSTDC1 in NSCLC." (PMID 27087917, 2016). "SOSTDC1 might represent a tumor suppressor through inhibiting the proliferation of NSCLC cells by regulating p21Cip and p27Kip, which in turn affects Rb-E2F signaling." (PMID 27087917, 2016). "SOSTDC1 is down-regulated and suppresses tumor growth in NSCLC." (PMID 27087917, 2016). "Accumulating evidence has revealed that SOSTDC1 might act as a tumor suppressor in many cancers." (PMID 27087917, 2016). "Moreover, SOSTDC1 over-expression suppressed the growth of tumor xenografts in nude mice." (PMID 26378658, 2015). "In addition, SOSTDC1 expression was significantly correlated with the tumor size (p=0.038)." (PMID 26378658, 2015). "In summary, this study suggests that SOSTDC1 promotes TNBC progression, as well as mediates Olaparib resistance of both BTICs and bulk‐tumor cells." (PMID 38864559, 2024). "We then set out to detect the expression of SOSTDC1, and found that the expression of SOSTDC1 was higher in TNBC patient tumor samples as well as TNBC cell lines." (PMID 38864559, 2024). "SOSTDC1, TLR5, MT1G, and MUC6 were downregulated in locally advanced tumor tissue samples, whereas COL8A1 and THBS2 were upregulated (P<0.05)." (PMID 36969001, 2023). "We found that the gene expression of SOSTDC1, HMGA2, and FHL1 was significantly higher in tumor tissues than their paired adjacent normal tissues from 31 PRCC patients in TCGA database, especially that of HMGA2 (p < 0.001)." (PMID 37283291, 2023). "SOSTDC1 and DACT2 did show prominent differential methylation in DCIS and invasive BC, but methylated WIF1 was significantly increased (P = 0.031) in DCIS tumours." (PMID 34997107, 2022). "Elevated methylation intensity of SOSTDC1, DACT2 and WIF1 was observed in patients who had advanced tumour stage, positive nodes and local or distant metastasis." (PMID 34997107, 2022). "Some of the tumour suppressor genes identified in our study included Lactotransferrin (LTF), MFNG and SOSTDC1." (PMID 21092330, 2010). "even pinpointed potential tumor suppressors located on 7p: TWIST1 and SOSTDC1." (PMID 40439002, 2025). "Also, other genes associated with metastasis and cancer progression were differentially regulated in tumour tissue, i.e., MMP13, WNT5B, and SOSTDC1." (PMID 39202425, 2024). "In agreement with the TCGA data, decrease in SOSTDC1 mRNA levels was observed in most tumor tissues as compared with that in their adjacent non-tumorous lung tissues." (PMID 27087917, 2016). "Our results showed that SOSTDC1 was down-regulated in 90 tumor tissues as compared to their adjacent non-cancerous lung tissues." (PMID 27087917, 2016).
tumor (continued). "In the context of understanding the possible role of SOSTDC1 in NSCLC development and progression, our current study led to findings that the protein is down-regulated in NSCLC and might play a tumor-suppressive role." (PMID 27087917, 2016). "However, we could not draw definitive conclusions of the relationship between SOSTDC1 protein level and BRCA1 mutation since there was no available information on BRCA1 status in the TNBC patient tumor samples we used in this study." (PMID 38864559, 2024).
cancer (17 papers, 2010 to 2024). A tumor composed of atypical neoplastic, often pleomorphic cells that invade other tissues. "SOSTDC1 has been identified as having a strong correlation with the development and progression of various cancer types, such as breast, kidney, gastric, and thyroid cancers." (PMID 38012244, 2023). "Another study revealed that Sostdc1 overexpression inhibited NSCLC cell proliferation, migration, and invasion, along with the osteoclastogenesis induced by cancer cells, whereas Sostdc1 knockdown had the opposite effect." (PMID 36338475, 2022). "Sostdc1 has been widely studied in the development of tooth, bone fracture, cancers, kidney disease, vasculature, and hair follicle formation." (PMID 36338475, 2022). "Sostdc1 inhibits the proliferation of related cancer cells through its methylation, BMP signalling pathways, and other mechanisms." (PMID 36338475, 2022). "This article summarises the role of Sostdc1 in skeletal biology and related cancers to provide a theoretical basis for the treatment of related diseases." (PMID 36338475, 2022). "In this review, we summarise the role of Sostdc1 in the skeletal system and the development of cancers, providing novel insights into its potential mechanisms of action." (PMID 36338475, 2022). "NK cells are innate-like lymphocytes that eliminate virus-infected and cancerous cells, suggesting that Sostdc1 plays an important regulatory role in related cancers." (PMID 36338475, 2022). "Recent studies have highlighted that epigenetic modifications result in Sostdc1 downregulation in cancer." (PMID 36338475, 2022). "The expression of known cancer-related genes such as Sostdc1, S100a4, Crabp2, and Id3 was significantly upregulated in the cancer stem-like cell cluster." (PMID 34785704, 2021). "Previous experimental research has reported that low expression of SOSTDC1 in NSCLC cells promoted cancer cells-induced osteoclast differentiation." (PMID 34136487, 2021). "Several novel genes including Sostdc1, S100a4, Crabp2, and Id3 were identified among the top upregulated genes in the cancer stem-like cell population." (PMID 34785704, 2021). "Sostdc1 plays many roles in development of tissues (including development of the eye) and in promoting cancer." (PMID 33322152, 2020). "In this study, we found that SOSTDC1 is downregulated in TC and that it suppresses proliferation of cancer cells." (PMID 30250199, 2018). "Of note, various mechanisms have been proposed to contribute to the down-regulation of SOSTDC1 in cancers." (PMID 27087917, 2016). "The role of sclerostin in cancer and SOSTDC1 (sclerostin domain containing 1)-expression in cancerous tissue was addressed in several studies." (PMID 27666393, 2016). "Recently, down-regulation of SOSTDC1 expression by epigenetic mechanisms, such as methylation, has been documented in cancer." (PMID 26378658, 2015). "Sostdc1 regulates the development of cancers through BMP signalling pathways." (PMID 36338475, 2022). "However, the potential role of Sostdc1 as a therapeutic target in related cancers requires further investigation." (PMID 36338475, 2022). "Studies have shown that silencing of SOSTDC1 is correlated with cancer progression." (PMID 30250199, 2018). "DNA methylation was observed in K1 and 8505C cancer cells, which exhibited low SOSTDC1 expression." (PMID 30250199, 2018). "SOSTDC1 negatively regulates BMP (bone morphogenetic protein) signaling during cell proliferation, differentiation, and apoptosis, and also regulates various processes in development and cancer by regulating the Wnt pathway." (PMID 36778919, 2023). "For example, several genes from the final part of the ranking, present specific clear information on MCC against the rest skin states as LGR5, POU4F1, SOSTDC1, KRT20, TGM3 and MYO15A genes, as their gene expression levels are opposite against to the other cancer-related skin states." (PMID 29750795, 2018).
cancer (continued). "For example, although MCC shows expression values contrary to the rest of skin states in the identified DEGs, there are genes like LGR5, POU4F1, SOSTDC1, KRT20 and MYO15A which are clearly postulated as differentiating genes in MCC diagnosing in comparison to other cancer-related skin states." (PMID 29750795, 2018). "Compared with PARP inhibitor or Cisplatin, SOSTDC1 knockdown did not impact cell sensibility to Docetaxel (DTX), which stops the growth of cancer cells by interfering with microtubules and blocking cell division." (PMID 38864559, 2024).
kidney disease (6 papers, 2009 to 2024). "However, interestingly, a previous systematic review concluded that Sostdc1 inhibits the progression of kidney-related cancers but promotes some kidney diseases, including acute and chronic renal injuries, and renal fibrosis." (PMID 36338475, 2022).
neurodegenerative disease (1 paper, 2019). A disorder of the central nervous system characterized by gradual and progressive loss of neural tissue and neurologic function. "We have observed significant downregulation of Sostdc1 gene on the exposure of gamma radiation, which suggests radiation causes significant changes in the WNT signaling pathway, and this might ultimately lead to various hippocampus-induced neurodegenerative diseases." (PMID 32231775, 2019).
SOSTDC1 also shares sentences with these, for which no sentence is quoted: tooth agenesis (4 papers); adenocarcinoma (2); kidney damage (2); renal fibrosis (2); Ureteral obstruction (2); benign diseases of the breast (1); clear cell carcinoma (1); cleft palate (1); diabetic nephropathy (1); gastric tumors (1); glioma (1); glomerular disease (1); goiter (1); iron deficiency (1); lung adenocarcinoma (1); lung carcinoma (1); osteoporosis (1); pancreas cancer (1); pituitary tumor (1); renal cell carcinoma (1); squamous cell carcinoma (1); type 2 diabetes (1).